CASP1 (caspase 1)
Diseases named in the same sentence as CASP1 in open-access papers (continued):
Sharing a sentence is not in itself a finding about the gene and the disease.
inflammation (continued). "Next, we used caspase-1 inhibitor to further investigate the role of caspase-1-IL-1 cascade in ozone-induced airway inflammation and in IL-17A+ γδT-cells generation." (PMID 26739627, 2016). "In mouse models of cigarette smoke-induced pulmonary inflammation, caspase-1 knockout mice had significantly lower levels of IL-1β compared to wild-type mice, which suggests that caspase-1 is critical in pulmonary inflammation." (PMID 26496436, 2015). "Nlrp3 contributes to renal inflammation through its classical function of caspase-1-mediated cleavage and subsequent release of effector cytokines." (PMID 24454932, 2014). "The role of caspase-1 for intrarenal IL-1β and IL-18 processing and postischemic renal inflammation was documented a decade ago, but the triggers for caspase-1 activation remained enigmatic." (PMID 22046355, 2011). "The NLRP3 inflammasome-mediated activation of caspase-1 contributes to a large spectrum of inflammatory diseases but so far little is known about its role in renal inflammation." (PMID 22046355, 2011). "More importantly, we have demonstrated in animal experiments that the protective effect of IAld on intestinal inflammation is associated with the NLRP3 inflammasome, as IAld treatment significantly reduced the LPS-induced expression level of the caspase-1 protein, an NLRP3 inflammasome effector." (PMID 39334766, 2024). "The activation of intracellular PRRs in cardiomyocytes leads to inflammasome activation, which converts pro-caspase-1 into the catalytically active protease that is responsible for the production of IL-1β and IL-18, subsequently triggering cardiac inflammation." (PMID 36978920, 2023). "The aim of this study was to determine whether activation of the P2X7/caspase 1 pathway has a functional role in CS-induced airway inflammation." (PMID 21915284, 2011). "We hypothesized that neonatal hyperoxia exposure induces cardiovascular inflammation, systemic vascular stiffness, and cardiopulmonary damage, and moreover, that caspase-1 inhibition is a therapeutic strategy to prevent cardiovascular inflammation, fibrosis, and BPD." (PMID 41231039, 2025). "Therefore, we speculated that GSDMD may induce pyroptosis under the regulation of caspase-1, which may mediate the occurrence and development of renal inflammation and eventually lead to renal function damage." (PMID 35577353, 2022). "In our present study, TA had a beneficial effect on renal inflammation in DN mice by reducing the release of pro-inflammatory cytokines, along with suppressing the NLRP3/ASC/Caspase-1 signaling pathway, and further reduces renal interstitial fibrosis." (PMID 39193336, 2024). "The administration of the caspase-1 inhibitor z-YVAD-fmk or caspase-1 in mice suppresses BLM-induced IL-1β production, lung inflammation, and fibrosis." (PMID 36834561, 2023). "Animal models of lipopolysaccharide-induced amniotic inflammation showed increased mRNA expression of inflammatory-related genes (NLRP3, Caspase-1, IL-1β), and higher concentrations of NLRP3 protein in fetal membranes and deciduae than before preterm delivery." (PMID 37571360, 2023). "Recently, it is shown that GSDMD-dependent pyroptosis is triggered in silica-treated AMs by activating the TLR4/NLRP3/caspase-1/GSDMD pathway, which results in aggravated pulmonary inflammation and diffuses silicon nodules." (PMID 35819638, 2022). "SZF suppresses the activation of the NLRP3-ASC-caspase-1 axis by inhibiting TXNIP, thus ameliorating renal inflammation." (PMID 29358971, 2017). "In conclusion, the study identified a potential P2X7R antagonist, Z1456467176, that can inhibit ATP-induced NLRP3-caspase-1-IL-1β pathway activation by allosterically modulating P2X7R, effectively alleviating MSU crystal-induced gouty joint inflammation in rats." (PMID 36052144, 2022).
inflammation (continued). "In addition, amniotic fluid concentrations of CASP-1 were increased in women who underwent spontaneous preterm labor with intra-amniotic inflammation compared with those without intra-amniotic inflammation." (PMID 35993366, 2022).
neurodegenerative disease (28 papers, 2016 to 2026). A disorder of the central nervous system characterized by gradual and progressive loss of neural tissue and neurologic function. "Increased caspase-1 expression is associated with various neurodegenerative diseases and BBB dysfunction." (PMID 38473954, 2024). "The NLRP3 inflammasome complex triggers caspase-1 activation, which is one of the causes of the pathogenesis of neurodegenerative diseases." (PMID 32751738, 2020). "Elevated IL-1β, IL-18, and inflammasome proteins such as ASC and caspase-1 have been reported in neurodegenerative disease and TBI, often correlating with severity or outcome." (PMID 41511361, 2026). "ASC and caspase-1 are major components of the inflammasome pathway, which plays a critical role in several neuroinflammatory and neurodegenerative diseases including MS17,22,31,42." (PMID 37414913, 2023). "Afatinib, an orally available EGFR tyrosine kinase inhibitor, inhibits EGFR activation to alleviate neuroinflammation by reducing caspase 1 activation and interleukin-1β levels in neurodegenerative diseases." (PMID 32231518, 2020). "Accordingly, inhibition of caspase-1 prevents the development and worsening of multiple neurodegenerative diseases." (PMID 33584203, 2020). "Increasing evidence implicates the NLRP3 inflammasome and its activation/release products; ASC specks, caspase-1 and IL-1β in the pathogenesis of neurodegenerative disease and stroke." (PMID 29654318, 2018). "NLRP3 inflammasome activation, assembled by NLRP3-ASC-caspase-1, may drive neurodegenerative diseases." (PMID 37238000, 2023). "Therefore, caspase-1 is a possible target for neurodegenerative diseases or BBB restoration." (PMID 38473954, 2024). "Neuronal caspase-1 from inflammasome and cathepsin B are key enzymes mediating neuroinflammation in AD, therefore, revealing new molecules to modulate these enzymes may be an interesting approach to treat neurodegenerative diseases." (PMID 36286438, 2022). "In neurodegenerative diseases, amyloid proteins trigger NLRP3 inflammasome, leading to activation of CASP1 and release of IL-1β." (PMID 37578928, 2023). "Given that mature IL-1β secretion has been shown to be a key mediator in inflammation-induced neuronal apoptosis in neurodegenerative disease, our mechanistic finding suggests that pharmacological inhibition of NLRP3 may alleviate inflammation through Caspase 1 dependent mature IL-1β secretion." (PMID 35431795, 2022).
neurological diseases (23 papers, 2013 to 2025). "This positional advantage, combined with the superior binding energy, positions Vitexin as a more effective caspase-1 inhibitor with enhanced anti-inflammatory capabilities relevant to neurological disorders." (PMID 41351800, 2025). "Among these, the NLRP3 inflammasome is the most studied regulator of caspase-1 activation related to sterile inflammation in neurological diseases." (PMID 37353794, 2023). "CASP1 is a key mediator of cell pyrolysis and participates in the inflammatory response and the development of various neurological diseases." (PMID 35198034, 2022). "NLRP3/caspase-1 axis activation and pyroptosis have been shown to play vital roles in neuroinflammation and neuronal damage in various neurological disease models." (PMID 34666787, 2021). "Caspase-1 activation functionally links vascular and neurological diseases and hence represents a promising therapeutic target." (PMID 32907600, 2020). "Considering the crucial role of microglial inflammasome/caspase-1/IL-1β axis in neuroinflammation, we propose that the inhibition of DAPK1 represents a potential therapeutic application for IL-1β-associated neurological diseases." (PMID 29967321, 2018). "Upregulated NLRP3 expression may enhance caspase-1-mediated inflammatory cascades and further stimulate the production of downstream inflammatory molecules, including IL-1β, IL-6, and TNF-α, all of which lead to an inflammatory response in a variety of neurological diseases." (PMID 36364939, 2022).
metabolic disease (22 papers, 2013 to 2025). A congenital disorder (due to inherited enzyme abnormality) or acquired (due to failure of a metabolically important organ) disorder resulting from an abnormal metabolic process. "Other inflammasomes and molecules related to the activation cascade (e.g., CARD8, AIM2, IFI16, CASP-1, and IL-1β) have also been found to be associated with a variety of infections and metabolic diseases." (PMID 36105941, 2022). "Aberrant or excessive activation of the classical caspase-1 path is associated with many autoinflammatory, autoimmune, and metabolic diseases." (PMID 36110207, 2022). "The present study provided new evidence to show the direct contribution of NLRP3 inflammasome in the pathogenesis of DCM, which was associated with the IL-1β-related metabolic disorder and caspase-1-mediated pyroptosis in myocardium." (PMID 25136835, 2014). "NLRP3 inflammasome formation promotes the proximity-induced autocatalytic activation of caspase-1 and mediates the cleavage/activation and secretion/release of the pro-inflammatory cytokines IL-1β and IL-18 implicated in several metabolic disorders." (PMID 23924318, 2013). "Although research is still limited about the involvement of caspases in pregnancy-related inflammatory disorders, it has already been explored that caspase 1 can play a role in the specific context of preterm birth and maternal metabolic disorders." (PMID 38791563, 2024). "It has been reported to play an important role in autoimmune and metabolic diseases by activation of CASP1 and production of IL-1β and IL-18." (PMID 36694200, 2023). "On this scenario, anti-IL-1 therapies proved the potential of inhibiting proinflammatory caspase-1, pathogenic step characteristic for CMS occurrence, associated with aberrant inflammasome signaling, raising a new horizon for metabolic diseases management." (PMID 33172097, 2020). "Inflammasome activation leads to maturation of caspase-1 and processing of IL1β, contributing to many metabolic disorders and directing adipocytes to a more insulin-resistant phenotype." (PMID 27321128, 2016). "This is in agreement with previous findings that neutrophil elastase KO mice have reduced levels of IL-1β in the liver and serum and that diminished NLRP3 inflammasome and caspase-1 activity elicits protection from high-fat diet mediated metabolic disorder." (PMID 26405763, 2015). "Caspase-1 activation is a central event in inflammasome signaling, and it plays a pivotal role in chronic low-grade inflammation, a well-recognized contributor to the pathogenesis of metabolic diseases such as T2D." (PMID 41225798, 2025). "Notably, the modulation of Cd36-Pparg pathways provides attractive options for the treatment of metabolic diseases, where caspase-1 is also a potential target molecule." (PMID 34502478, 2021). "In this scenario, anti-IL-1 therapies proved to have therapeutic effect in inhibiting proinflammatory caspase-1, pathogenic element characteristic for CMS, and associated with aberrant inflammasome signaling, resulting in a new horizon for metabolic diseases treatment." (PMID 33172097, 2020). "Further, via these molecular pathways, caspase-1 may induce developmental disorder, hereditary disorder, metabolic disease, ophthalmic disease, and organismal injury and abnormalities." (PMID 28153032, 2017). "Interestingly, we found that SA also could regulate the balance of gut microbiota and its metabolism disorder in NASH rats by inhibiting NLRP3/ASC/caspase-1 axis." (PMID 38026986, 2023). "This indicates that caspase-1 may have a profound effect on lipid metabolism through IL-1β and IL-18 pathways, suggesting that it might play a significant role in adipose tissue as well as in metabolic diseases." (PMID 28153032, 2017).
metabolic disease (continued). "Since caspase 1 is an important regulator for the maturation of these cytokines during inflammasome activation, many studies have started to investigate the role of this protein in the development of obesity, NAFLD, and other metabolic disorders." (PMID 31998283, 2019). "However, in the current study, we could not observe any significant changes in the expression of caspase-1 substrates in different cellular compartments in metabolic diseases." (PMID 27842563, 2016).
cardiovascular disease (20 papers, 2013 to 2025). "The NLRP3 inflammasome, a cytosolic complex found in pro-inflammatory immune cells, has been implicated in several cardiovascular diseases and is responsible for the processing and release of IL-1β using active caspase-1 (CASP1)." (PMID 39763850, 2024). "Pyroptosis is an important natural immune response depending on activated caspase-1 and is associated with distortion to cell integrity, cell swelling, and the release of intracellular proinflammatory cytokines, that leads to the progression of cardiovascular diseases." (PMID 37762315, 2023). "Evidence for pyroptosis in I/R injury comes from studies with caspase-1 inhibitors, which reduce cardiac I/R injury 36 and the IL-1β inhibitor, Canakinumab, which in humans has shown to result in a 15% reduction in mortality associated with all cause cardiovascular disease." (PMID 33878183, 2022). "NLRP3, which has received the most study in cardiovascular disease, has been linked to increased IL-1β (IL1B) production and caspase-1 activity, as well as impaired cardiac function." (PMID 40332346, 2025). "Pyroptosis, dependent on inflammatory caspases (caspase-1, 4/5/11), contributes to cell death in inflammatory diseases, cardiovascular disorders, CNS diseases, and tumors." (PMID 41377919, 2025). "Inflammasome-mediated caspase-1 activation results in a proinflammatory form of programmed cell death, pyroptosis, a catastrophic form of cell demise in cardiovascular diseases." (PMID 37240345, 2023). "CASP1-dependent pyroptosis plays a pivotal role in the pathogenesis of cardiovascular disease and can be observed in endothelial cells, macrophages, and so on." (PMID 35354793, 2022). "Caspase-1 inhibitors can also inhibit pyroptosis, and thus, serve to be useful in the treatment of cardiovascular diseases." (PMID 35673561, 2022). "Thus, an increasing number of experiments, both in vivo and in vitro, have proven the role of caspase-1 in cardiovascular disease, and a possible new strategy for their treatment is the use of drugs to inhibit pyroptosis." (PMID 41231039, 2025). "As a cytoplasmic receptor, NLRP3 responds to a series of molecules related to cellular ROS level and excessive production of pro-inflammatory cytokines, and mediates caspase-1-dependent programmed cell death, called pyroptosis, that plays an important role in cardiovascular disease." (PMID 35715805, 2022).
kidney disease (20 papers, 2011 to 2025). "Caspase-1 is a key inflammatory enzyme in the activation of inflammasomes, which are multi-protein complexes that respond to cellular damage and stress in kidney diseases." (PMID 41463113, 2025). "The NLRP3–ASC–caspase-1–IL-1β–IL-18 pathway has been identified as a factor in the development of the pathophysiology of numerous kidney diseases." (PMID 38740765, 2024). "Despite the validation of various CASP-1 inhibitors in animal models of kidney disease, their utilization in humans is constrained due to their unfavorable toxicity profiles." (PMID 38229085, 2024). "The effectiveness of inhibitors targeting caspase 1 has been studied in animal models of kidney disease." (PMID 38740765, 2024). "Pyroptosis is probably involved in kidney diseases through two pathways: the caspase-1-mediated canonical pathway and the caspase-4/5/11-mediated noncanonical pathway." (PMID 34007404, 2021). "Recent studies document the role of the NLRP3 inflammasome-caspase-1-IL-1β/IL-18 axis in kidney disease." (PMID 22701621, 2012). "To determine whether the inflammasome was activated in proteinuric kidney disease, we first detected the intensity and distribution of caspase-1, IL-1β and IL-18 staining which were the markers of inflammasome activation in the human renal biopsies." (PMID 23977286, 2013). "Within the studies concerning pyroptosis in the field of kidney diseases, several have focused on proteins related to the pyroptosis signaling pathway, that is, NLRP3, caspase-1, and the inhibitor or activator of GSDMD." (PMID 34007404, 2021). "The relatively higher expression of CASP4, CASP11, and GBPs compared to CASP1, PYCARD, and NLRP3, however, may suggest a more prominent role of non-canonical versus canonical inflammasome activation contributing to kidney disease." (PMID 38838223, 2024). "Focal cell death contributes to renal disorders through two primary pathways: the classical pyroptosis pathway mediated by caspase-1 and the non-classical pyroptosis pathway facilitated by caspase-11." (PMID 39839617, 2024). "In addition, although it has been reported that NLRP3 inflammasome can negatively regulate autophagy through caspase-1, the role and mechanism of NLRP3 inflammasome inhibition of autophagy in renal diseases need to be further clarified." (PMID 34884572, 2021).
infectious disease (12 papers, 2011 to 2023). A disorder directly resulting from the presence and activity of a microbial, viral, or parasitic agent in humans. "P2Y2R and P2X7R have been linked to IL-1β release in a caspase-1-dependent way during infectious diseases." (PMID 38239348, 2023). "Additionally, the disease/function networks that associated with AGE downregulated Casp1, Tlr3, Serp1, Irf1, Irf5, and Irf7 genes were involved in the antimicrobial response, inflammatory response, and infectious diseases." (PMID 27734935, 2016). "Nevertheless, although pyroptosis has this protective host response to infectious diseases, exaggerated caspase-1 activation can be detrimental to the surrounding tissues." (PMID 35008798, 2021). "Caspase-1 inhibitors, including VX-765, are also used in the treatment of CVDs and infectious diseases." (PMID 34484243, 2021). "Previous work has implicated caspase-1 and IL-18 in this infectious disease although the pathways that led to their activation were not investigated." (PMID 22241982, 2011). "However, some reports demonstrated that the peritoneal macrophages express IL-18 precursor and usually activate during infectious diseases because most pathogens trigger the synthesis of mature IL-1β, which, in turn, activates caspase-1 to cleave pro-IL-18 to mature IL-18, which is then secreted." (PMID 36145686, 2022). "However, in untreated infected mice, changes of levels of NLRP3, a target protein of NF-κB that plays a key role in immune responses to infectious diseases, paralleled changes of phosphorylated NF-κB levels, leading to cleavage of pro-caspase-1 and triggering of the inflammatory cascade." (PMID 34950611, 2021).
kidney (11 papers, 2017 to 2025). "TLYS treatment reduced the expression of NLRP3 and caspase-1 in rat kidney tissues, as well as the expression of inflammatory factors, and the interstitial fibrosis of the kidney." (PMID 35873572, 2022). "Here, we investigated the role of caspase-1-mediated pyroptosis in BD-induced kidney injury in rats." (PMID 34901142, 2021). "Suppresses NLRP3, caspase-1 and ASC expression and prevents acute kidney injury induced by lipopolysaccharide." (PMID 35566359, 2022). "In conclusion, our results verify the reno-protective potential of AEA against HgCl2-induced kidney injury by its anti-inflammatory, antioxidant, and anti-apoptotic capacities by modulating WNT-5A/BCL-2, IP3/NFATC1, HMGB-1/RAGE/NF-κB, caspase-1/IL-18, and caspase-3/BCL-2 cues." (PMID 37488162, 2023).